DAPK1-IT1 (DAPK1 intronic transcript 1)
Gene: Long non-coding RNA gene on chromosome 9 (87,553,454 to 87,554,459, forward strand). Ensembl gene ENSG00000236709.
Diseases named in the same sentence as DAPK1-IT1 in open-access papers:
DAPK1-IT1 is named in the same sentence as 2 diseases in open-access papers, as found by Europe PMC text mining. Sharing a sentence is not in itself a finding about the gene and the disease.
DAPK1-IT1 shares sentences with these, for which no sentence is quoted: cancer (1 paper); diabetes (1).